EGFR (epidermal growth factor receptor)
Diseases named in the same sentence as EGFR in open-access papers (continued):
Sharing a sentence is not in itself a finding about the gene and the disease.
tumor (continued). "2D proliferation assays showed that in the absence of EGFR inhibition, lack of activation of the ERK1/2 pathway led to a strong decrease in cell growth while impairment of the AKT pathway reduced cell numbers less efficiently, except in ErbB2 tumor cells." (PMID 23028720, 2012). "Also, as with IDH1 staining, no cells lining the vessels showed increased EGFR copy number using CISH, supporting the concept that the endothelial lining was not derived from the surrounding tumor." (PMID 22298889, 2012). "However, also freshly isolated tumor cells but not fibroblasts from HNSCC patients responded to VPA/HU administered at therapeutically achievable levels (0.5-1.5 mM) with BIM induction, EGFR downregulation and apoptosis." (PMID 22289787, 2012). "Immunohistochemical analysis showed that DKAT cells did not stain for ER/PR but stained positively for EGFR, and fluorescence in situ hybridization demonstrated diploid copy number of HER2, consistent with the triple-negative primary human tumor (data not shown)." (PMID 23049838, 2012). "In tumour no 11, the LAIR results for chromosome 7 were interpreted as three chromosomal copies in an imbalanced state (allelic state [AAB]) while FISH clearly showed a mixture of three and four copies, both for the centromeric and the EGFR specific probes." (PMID 22675538, 2012). "Inhibition of ErbB signalling, even when targeting both EGFR and ErbB3, may not be sufficient to effectively halt PDAC tumour progression." (PMID 21792199, 2011). "At the same time, membrane and nuclear EGFR expression in CRC, according to our knowledge, has not been published so far, and the present study was conducted with the aim to explore the correlation between mEGFR, nEGFR and cyclin-D1 expression on tumor cells." (PMID 22050898, 2011). "Furthermore, in clinical trials evaluating the efficacy of cetuximab, treatment response was not related to the levels of EGFR expression, since many patients with EGFR expressing CRC failed to respond, or those with EGFR negative tumor responded to therapy." (PMID 22050898, 2011). "However, when the definition of 5NP tumours was restricted to those that were negative for both CK5/6 and EGFR, there was little difference in the hazard ratio estimates (unpublished data." (PMID 20520800, 2010). "Also, while trials utilizing the farnesyl transferase inhibitor lonafarnib (Sarasar), which targets RAS, are underway, none are currently examining the combination of EGFR and RAS inhibition in any tumor type." (PMID 20037743, 2010). "It was found that β-glucan exerts similar anti-tumor effects irrespective of antigens (GD2, GD3, CD20, epidermal growth factor-receptor, and HER-2) or human tumor types (neuroblastoma, melanoma, lymphoma, epidermoid carcinoma, and breast carcinoma) or tumor sites (subcutaneous versus systemic)." (PMID 19515245, 2009). "Hence, the results suggested a correlation between the therapeutic efficacy of gene gun administration of non-coating EGFR DNA vaccine and the amount of CD8+ T cell tumor infiltration." (PMID 19178753, 2009). "High levels of activated c-Src in DCIS was associated with HER2 positivity (P<0.0005), high tumour nuclear grade (P<0.0005), the presence of comedo necrosis (P=0.001) and high Ki67 scores (P=0.025), but not with ER status (P=0.973), tumour size (P=0.403) and EGFR/HER1 expression (P=0.507)." (PMID 17060931, 2006). "Severity of skin rash most likely relates to the number of EGFR homodimers in the skin and may not always represent the HER-kinase signaling status in a coexisting tumour." (PMID 16306877, 2006). "Quantitative analysis revealed that EGFR-BsTe secretion abrogated EGFR upregulation and enhanced B7-H3 downregulation in a target-dependent manner; however, efficacy was diminished when the CAR-Target (B7-H3) was absent on a substantial fraction of tumor cells." (PMID 42301527, 2026).
tumor (continued). "Co-culture with B16 ffLuc GFP EGFR cells for 24 h induced the secretion of approximately 4 pg/mL of IL-2 and 3.5 × 103 pg/mL of interferon-gamma (IFN-γ) by EGFR mCAR T cells, while no significant cytokine release was detected in cultures without antigen-positive tumor cells." (PMID 41516067, 2025). "Importantly, targeted inhibition of EGFR and/or MET does not affect FER expression, suggesting that FER may sustain invasive tumor growth independently of specific GFR antagonism." (PMID 41115375, 2025). "Tumor uptake of [64Cu]Cu-NOTA-trastuzumab Fab-PEG24-EGF bsRICs was 1.7-fold higher in SK-OV-3 tumors homogeneously expressing HER2 (8.2 ± 1.7% ID/g) than in tumors with heterogeneous HER2 and EGFR expression but this difference was not significant (4.8 ± 0.6% ID/g; p > 0.05)." (PMID 38711454, 2024). "The expression of EGFR, as well as most solid tumor antigens, is not restricted to malignant cells only; thus, multiple CAR T cell approaches have been tested with the aim to limit the on-target, off-tumor toxicities of for instance EGFR-targeting CAR T cells and increase their safety." (PMID 38203786, 2024). "In these cases, an anti-EGFR with or without irinotecan is used in the third-line setting, followed by TFD/TPI with bevacizumab or regorafenib in later lines for human epidermal growth factor receptor 2 (HER2)-negative tumours and by anti-HER strategies for HER2-positive tumours." (PMID 37377686, 2023). "A series of bispecific antibodies combining anti-CD47 specificity with anti-PD-L1, -EGFR, -CD19, or -CD20 activity may preserve tumor-specific phagocytosis-stimulating activities while sparing the host cells that do not express the tumor antigen, thus limiting toxicity." (PMID 38033495, 2023). "Though this model does not allow for evaluation of long-term tumor recall, as the syngeneic murine system enabled, it facilitated evaluation of the impact of BsAb on ATC-specific trafficking and phenotype since there are no circulating T-cells in control or anti-EGFR alone treated animals." (PMID 35177811, 2022). "iPSC-NK cells expressing the CD64/16A chimeric receptor killed EGFR+/HER2+ SKOV3 ovarian cancer cells when combined with the anti-HER2 therapeutic mAb trastuzumab, or the anti-EGFR1 monoclonal antibody cetuximab, while little anti-tumor activity killing was seen without addition of these antibodies." (PMID 35185932, 2022). "Thus, even if EGFR was overexpressed with NONO knockout, tumor phenotype was partly restored." (PMID 35013116, 2022). "However, it is possible that without inhibiting EGFR, the impact of PEPDG278D on HER2 may be negated by rapid tumor growth." (PMID 35650607, 2022). "Finally, in TKKK, the EGFR amplification could not be confirmed on the protein level, while the ERBB2 amplification clearly prevailed in tumor biology in this case." (PMID 36013219, 2022). "Operable patients with EGFR CNG positive tumours (high polysomy or amplification) had shorter median overall survival (284 days, 95% CI 284.5–737.5) than patients with EGFR CNG negative tumours (905 days 95% CI 566.9–1243.1), HR 1.51, 95% CI 1.09–2.12, p = 0.016)." (PMID 33169187, 2021). "Therefore, the use of anti-EGFR therapeutics, such as cetuximab, is a promising strategy of altering the TIME towards tumor recognition and potentially killing rather than evasion and tumor growth." (PMID 34557197, 2021). "Patients with EGFR-amplified tumours (ddPCR CNV score ≥2) also had a lower median OS of 9.74 months (95% CI 3.68 to 11.35 months), compared with 11.18 months for patients with EGFR non-amplified tumours (95% CI 8.78 to 13.16 months) (HR 1.28 (95% CI 0.77 to 2.13); p=0.35)." (PMID 33199443, 2021). "Whilst patients with epithelial CMS2/3 tumours benefit from anti-EGFR agents given as monotherapy or combined with an oxaliplatin-based chemotherapy regimen, patients with CMS4 tumours appear to have no or even a detrimental effect when anti-EGFR is added to an oxaliplatin-based regimen." (PMID 34253874, 2021).
tumor (continued). "The expression levels of mucin 1 (MUC1), epidermal growth factor receptor (EGFR), epithelial cell adhesion molecule (EpCAM), and extracellular matrix metalloprotease inducer (EMMPRIN) in tumor-derived MVs were used to distinguish cancer patients from healthy controls regardless of tumor type." (PMID 33499132, 2021). "Here, we investigated genetic and nongenetic sources of variability in an in vitro tumor heterogeneity model comprising multiple versions (VU, MGH, and BR1) and single cell-derived sublines of the NSCLC cell line PC9 that exhibit a wide range of different responses to EGFR inhibition." (PMID 34061819, 2021). "Moreover, the 60 s kINPen plasma treatment, which reduced absolute lesion and tumor sizes significantly, was the only treatment not showing a reduction in ACVR1B, ACVR2A, CSF1, EGF, EGFR, IL15, and IL6RA when compared to all other treatments in the high dose DBP group." (PMID 34667240, 2021). "Although anti-EGFR agents do not confer any benefit to pre-treated BRAF-mt mCRC patients, these results suggest that they might be of value in the first-line treatment of such patients, especially if the goal of the treatment is tumour shrinkage." (PMID 31353365, 2019). "In contrast to CWR22 tumours, LNCaP cells experienced increase in EGFR upon lapatinib treatment, likely reflecting variability of response of various HSPC models; whereas the response of CRPC models to lapatinib showing HER2 but not EGFR increase was consistent in all models used." (PMID 31209328, 2019). "Thus, the expression of PTEN was absent and the tumor cells could find independent on EGFR activation pathway, but effectively activate the PI3K pathway, resulting in resistance to EGFR-TKI treatment." (PMID 29455664, 2018). "In our current study, we found that icotinib-containing treatment was able to suppress activities of EGFR, MAPK, and Akt proteins; it was not total inhibition of protein phosphorylation, but reduction of tumor xenograft volume, and size may not be through suppression of these protein activities." (PMID 27852073, 2017). "Interestingly, neither AKT inhibitors nor EGFR‐TKI induce significant cell death by themselves, but in combination they are highly potent at inducing apoptosis, suggesting that their combined effects have lethal consequences for tumor cells." (PMID 28003335, 2017). "EGFR nuclear translocation positively correlates with features of tumor aggressiveness: A549 and GLC82 cells expressing wild type EGFR increase their clonogenicity and proliferation in response to PGE2 or EGF in contrast to cells expressing a mutant EGFR lacking its nuclear localization sequence." (PMID 28415726, 2017). "However, human lung tumour cells are heterogeneous and the proliferation status in different tumour cells may be affected by more complicated factors/pathways and are not solely affected by GPRC5A or EGFR." (PMID 27273304, 2016). "However, neither STAT3 activation nor anti-tumor activity of IL-6 antibody CNTO328 was observed in our HCC4006ER cells, suggesting that the IL-6/STAT3 pathway is not necessarily activated in EMT-related acquired EGFR-TKI resistance in NSCLC." (PMID 26789630, 2016). "While inhibiting a single pathway including EGFR and JAK/STAT3 was not sufficient to significantly block cell growth and survival, dual blockade of STAT3 and EGFR resulted in simultaneous attenuations of multiple survival pathways and dramatically increased anti-tumor activity in vitro and in vivo." (PMID 25928246, 2015).
tumor (continued). "When 3 of these tumor cell lines (SAS, HPC9Y and Calu-1) that expressed low levels of HER-3 were treated with an irreversible HER family broad inhibitor (dacomitinib, which inhibits EGFR, HER-2 and HER-4 but not HER-3), the expression of HER-3 was substantially increased." (PMID 26538233, 2015). "Transient oxygenation enhancements in the tumor were obtained after intravenous administration of the VEGFR targeting small molecule TKIs axitinib (Inlyta®) and sunitinib (Sutent®), but not following treatment with the EGFR targeting inhibitor erlotinib (Tarceva®)." (PMID 25758612, 2015). "It is concluded that blocking EGFR/EGFRvIII by cetuximab alone will most likely not translate into a clinical benefit, whereas incorporation of EGFR inhibitor signaling into a combined modality approach will more likely lead to improvement of GBM tumor control." (PMID 23383403, 2013). "Unfortunately, EGFR-TKI treatment was not effective in the tumor regression nor tumor marker level of present patient (disease might be controlled), but treatment with an ALK inhibitor resulted in SD with decreasing tumor markers." (PMID 23714228, 2013). "To rule out the possibility that the EGFR activation observed in LMS stem-like cells could result from culture-induced modifications, we investigated the activation state of the EGFR pathway in the original patient tumor." (PMID 23056514, 2012). "Patients receiving preoperative chemotherapy were less likely to present with EGFR-positive tumours than patients without preoperative chemotherapy (14 vs 40%, P=0.038), but no influence of preoperative chemotherapy on p-AKT or p-ERK tumour expression was found (both P>0.05)." (PMID 20683448, 2010). "Based on immunostaining data from the five markers used, overall 1820 tumours were classified as luminal A; 152 were luminal B; 165 were HER2; 266 were basal-like; and 118 tumours were unclassifiable (ER-negative/PR-/HER2-negative/EGFR-negative/CK5/6-negative)." (PMID 18681955, 2008). "Considering our results that TSPAN6 had no apparent effect on EGFR-induced proliferation but markedly altered invasive behavior in response to EGF, TSPAN6-regulated cell polarity and an EMT could conceivably explain why the modulation of TSPAN6 expression affects metastatic tumor spread." (PMID 35184157, 2022). "Thus, we may say that increased EGFR activity facilitates EMT and may be involved in the early stages of the process, but is neither necessary nor sufficient for the continued viability of the tumor as EMT progresses." (PMID 34162346, 2021). "We found ARF1 to be significantly higher in the WT tumor proteome (ARF1↑WT; no peptides/PSM in G12V vs. 10 peptides and 137 PSM in WT), which might represent an EGFR-independent activation of the RAS/MEK/ERK pathway and a potential escape mechanism for anti-EGFR therapy." (PMID 31805664, 2019). "Thus far, the targeted therapy against EGFR or EGFRvIII demonstrates only limited efficacy in GBM patients, partially due to the fact that, constitutive activation of the receptor well establishes its network to drive tumor progression, where the receptor itself is not the best target." (PMID 26717039, 2016). "Previously, we have proved that RBM5 expression was not directly regulated by EGFR, however, the results in the current study indicate that RBM5 might manipulate EGFR expression as an upstream gene, which may be a predominant mechanism by which RBM5 mediates tumor suppression." (PMID 25441176, 2014).
cancer (13,408 papers, 1988 to 2026). A tumor composed of atypical neoplastic, often pleomorphic cells that invade other tissues. "Non-mutant, i.e., wild-type (WT) RAS can also become activated through mechanisms such as gene amplification or excessive stimulation by mutated or overexpressed receptor tyrosine kinases (e.g., EGFR), thereby promoting cancer progression." (PMID 42279426, 2026). "For example, drugs targeting epidermal growth factor receptor (EGFR) mutations or BRAF mutations have been successfully used in the treatment of certain cancers." (PMID 41602372, 2026). "Mutations in the extracellular or intracellular domains of epidermal growth factor receptor (EGFR) are implicated in the development of various cancers." (PMID 41565660, 2026). "As a use case, pan-cancer analysis of the frequency of EGFR mutations was conducted with the graphical user interfaces of DORM, COSMIC, and cBioPortal databases." (PMID 41567248, 2026). "In a pan-cancer analysis of EGFR, DORM identified frequent mutations outside the kinase domain that are underrepresented in other databases." (PMID 41567248, 2026). "Mechanistically, CB2R loss enabled cancer cells to evade antitumor IFN-γ signaling while promoting a shift from HER2-CB2R to HER2-EGFR heterodimers, thus reducing dependence on HER2 and increasing reliance on EGFR-mediated pathways." (PMID 42115409, 2026). "A pan-cancer analysis of EGFR mutation frequencies was performed using DORM and other public databases." (PMID 41567248, 2026). "Given the frequency of EGFR mutations in human tumors, EGFRs have been proposed as a possible target for anti-cancer therapy." (PMID 40332381, 2025). "Solvent extracts from medicinal plants rich in various bioactive molecules, like flavonoids, alkaloids, etc., have been shown to modulate EGFR-signalling pathways and subsequently cause cell cycle arrest and/or regression of cancer growth." (PMID 40365309, 2025). "Recent findings indicate that EGFR-targeting ASO exhibits a more potent anti-cancer effect than traditional TKIs in NSCLC with EGFR mutations, including L858R and T790M, and can effectively suppress TKI-resistant patient-derived tumors." (PMID 40282505, 2025). "Overexpression of the EGFR gene and EGFR tyrosine kinase (EGFR TK) domain mutations have been linked to the development and progression of several cancers, including lung, colorectal, breast, brain, and pancreatic." (PMID 39031290, 2025). "Epidermal growth factor receptor (EGFR) is a representative cancer antigen associated with the progression of HNSCC, for which anti‐EGFR therapies are administered as first‐ or second‐line treatment." (PMID 40156197, 2025). "Cancer cells with abnormal activation and mutation of EGFR exhibit numerous characteristics that promote their survival and enable them to evade cancer immunotherapy." (PMID 40859900, 2025). "Altered GM3 levels are linked to cancer progression; their deficiency enhances EGFR activation and epidermoid carcinoma." (PMID 41369325, 2025). "Given the pivotal role of EGFR in cancer development and its close association with the efficacy of EGFR tyrosine kinase inhibitors, we investigated the influence of EGFR-derived circRNAs on cetuximab treatment." (PMID 41214390, 2025). "Dysregulated endocytic trafficking of EGFR can result in constitutively active EGFR signaling implicated in cancer pathogenesis." (PMID 39893205, 2025). "In these cancers, EGFR is overexpressed due to various mutations, which leads to an overactivation of EGFR." (PMID 40943615, 2025). "Elevated EGFR levels have a particularly strong association with the survival outlook of many cancers." (PMID 40574864, 2025). "This monoclonal should be considered in treatment trials of cancers with positive EGFR mutations yet showing anti-EGFR resistance." (PMID 40149288, 2025).